P4HA1 (prolyl 4-hydroxylase subunit alpha 1)
Diseases named in the same sentence as P4HA1 in open-access papers (continued):
Sharing a sentence is not in itself a finding about the gene and the disease.
tumor (continued). "Alpha 1 subunit of prolyl 4-hydroxylase (P4HA1) plays a key role in modulating the extracellular matrix component and promoting tumor progression by altering tumor adhesion, migration, and other biological behaviors in some cancers." (PMID 34680441, 2021). "According to the results, we found that P4HA1 mRNA highly expressed in most NSCLC cohort (24/31) compared with those in non-tumor tissues, except GSE11969, GSE39345, GSE31552, GSE43767, GSE63459, GSE19804." (PMID 34659558, 2021). "Our analysis in the TCGA‐LUAD Cohort demonstrated that P4HA1 mRNA expression was related with tumor diameter and distant metastasis." (PMID 34659558, 2021). "A six-gene risk score, the SCCHN TMI (SCCHN-tumor matrisome index: composed of MASP1, EGFL6, SFRP5, SPP1, MMP8 and P4HA1) was constructed and used to stratify patients into risk groups." (PMID 34830910, 2021). "To compare P4HA1 expression only in tumor tissues, we found that P4HA1 was highly expressed in KIRC and the lowest in KICH." (PMID 34966739, 2021). "We also proved that P4HA1 expression was positively correlated with TMB and MSI in these tumor types, implying a potential association with immunotherapy efficacy." (PMID 34966739, 2021). "The results demonstrated that P4HA1 expression was elevated in the relatively worse tumor stages in ACC, CESC, HNSC, KIRP, LUAD, PAAD, and THCA." (PMID 34966739, 2021). "As for tumor cell lines, we proved that P4HA1 expression was the highest in GBM cell lines using data from CCLE database." (PMID 34966739, 2021). "Subsequently, P4HA1 differential transcriptional levels were compared for the molecular and histological subtypes, tumor grades, and other BC patient factors." (PMID 33692831, 2021). "The single-cell RNA-seq analysis of the SCCHN TMI genes revealed that four of these genes (MASP1, EGFL6, SPP1, and P4HA1) are expressed in subpopulations of fibroblasts, macrophages, T cells and in tumor cells." (PMID 34830910, 2021). "P4HA1 has recently been found to overexpress in gliomas and HNSCC; its expression associated with tumor microvessel density." (PMID 33692831, 2021). "The overall assembly of COL‐IV networks around the tumor cells was also severely reduced in P4HA1‐KD tumors, as compared to the control tumors showing strong COL‐IV staining around tumor cells and cell nests." (PMID 32053263, 2020). "The Ki‐67 labeling indices varied from 70% to 90% in different regions of both the control and P4HA1‐KD tumors, apparently depending on the growth rates and cell cycle phases of the heterogeneous tumor cells." (PMID 32053263, 2020). "High P4HA1 expression in HNSCC tissues was significantly associated with alcohol consumption (P = .019), tumor location (P = .017), HPV infection (P = .011), tumor category (P = .006), lymphatic metastasis (P = .006), and pathological stage (P = .002)." (PMID 31782831, 2020). "Significantly higher P4HA1 expression was found in tumor tissues compared with normal tissues (P < 0.001)." (PMID 33299876, 2020). "To unravel the reasons for the larger tumor size in P4HA1‐KD tumors, we also stained the tumors for the cell proliferation marker Ki‐67." (PMID 32053263, 2020). "In the present study, we collected LUAD expression profile data from the TCGA database and GEO database and verified that P4HA1 expression was increased prominently in tumor tissues compared to normal tissues." (PMID 33299876, 2020). "When all CRC cases that include MSS and MSI subtypes are evaluated, age, tumor stage, and P4HA1 expression were found to be independent predictors for OS time." (PMID 32166002, 2020). "We used the Wilcoxon signed-rank test to probe the expression of P4HA1 in 57 paired tumor and adjacent normal tissues." (PMID 33299876, 2020). "The results showed that the expression of P4HA1 was significantly higher in tumor tissues than in normal tissues for LUAD patients." (PMID 33299876, 2020).
tumor (continued). "When only the CRC MSS subtypes were evaluated, tumor stage and P4HA1 expression were independent predictors for both OS and DFS times." (PMID 32166002, 2020). "In this study, we demonstrated that P4HA1 was upregulated in tumor tissues compared to normal tissues in LUAD." (PMID 33299876, 2020). "The control tumors showed diffuse CTHRC1 staining in tumor cells and a more prominent staining around tumor blood vessels, while the P4HA1‐KD tumors showed reduced CTHRC1 staining especially around tumor blood vessels." (PMID 32053263, 2020). "The number of cleaved caspase 3‐positive cells per tumor mm2 (calculated from the whole tumor sections) was significantly increased in the P4HA1‐KD tumors (fold 2.2, P = 0.008)." (PMID 32053263, 2020). "Reducing P4HA1 expression or blocking its activity with P4H inhibitors (P4Hi) significantly represses tumor progression in the three-dimensional (3D) culture system and xenograft models." (PMID 30367042, 2018). "The DOC treatment was stopped after three weeks, and tumor regrowth was significantly delayed in the P4HA1-silenced group." (PMID 30367042, 2018). "In the mouse xenograft model, LOXL4 knockdown increased primary tumor growth and lung colonization as well as collagen I and IV, lysine hydroxylase 1 and 2, and prolyl 4-hydroxylase subunit alpha 1 and 2 levels." (PMID 28060764, 2017). "Downregulation of P4HA1 upregualtes the expression of VEGF165b, suppresses intracranial tumor growth and blocks the transdifferentiation of GSCs into ECs, inhibiting tumor neovascularization." (PMID 28415787, 2017). "Meanwhile, an in vivo study demonstrated a significant inhibition of tumor growth and prolonged OS of xenograft mice due to downregulation of P4HA1." (PMID 28415787, 2017). "Chick chorioallantoic membrane (CAM) assay and mice xenograft investigations show that P4HA1 is required for tumor growth and metastasis in vivo." (PMID 25115393, 2014). "We identified multiple genes that were induced or repressed upon P4HA1 knockdown including those involved in tumor growth and invasion such as MMP1, MMP2 and FLRT3, among others." (PMID 25115393, 2014). "To assess the role of P4HA1 on tumor growth in vivo, we employed a chick chorioallantoic membrane assay (CAM) and measured spontaneous metastasis, including local invasion, intravasation, and metastasis to distant organs." (PMID 25115393, 2014). "P4HA1 expression was found to be associated with CRC progression and tumor immune infiltration." (PMID 41469036, 2025). "Our findings suggest that P4HA1 inhibition may enhance the efficacy of existing therapies by targeting the molecular underpinnings of tumor growth and immune modulation." (PMID 41469036, 2025). "Elevated levels of P4HA1 may facilitate tumorigenic processes by enhancing collagen deposition, which, in turn, promotes tumor cell invasion and metastasis." (PMID 41469036, 2025). "P4HA1 helps stabilize collagen and reorganize the matrix, promoting tumor cell growth and spread." (PMID 40959429, 2025). "P4HA1 knocking down inhibited CRC tumor growth, metastasis, and TAM infiltration polarization." (PMID 41469036, 2025). "Moreover, knocking down P4HA1 also reduced the increase in E‐cadherin expression and the decrease in Vimentin expression in tumor tissue." (PMID 41469036, 2025). "Notably, P4HA1 contributes to collagen stabilization and matrix remodeling, thereby promoting tumor progression and metastasis." (PMID 40959429, 2025). "We first analyzed the P4HA1 expression and the tumor immune infiltration in CRC." (PMID 41469036, 2025). "Prolyl 4‐hydroxylase subunit alpha 1 (P4HA1) has emerged as a pivotal enzyme in the regulation of collagen synthesis and subsequent remodeling of the extracellular matrix, processes that are crucial for tumor progression and metastasis." (PMID 41469036, 2025). "Moreover, P4HA1 and P4HA2 were associated with tumor stage, patient prognosis, and immune cell infiltration." (PMID 38806556, 2024).
tumor (continued). "While existing research on the relationship between P4HA1 and angiogenesis mainly focuses on its role in the transformation of tumor stem cells into ECs, the role of P4HA1 in post-ischemic angiogenesis and the underlying mechanisms remains unclear." (PMID 38238754, 2024). "P4HA1 stimulated glycolysis in tumor and normal cells through distinct pathways may be ascribed to the divergent reliance on glycolytic metabolism between these two cell types." (PMID 38238754, 2024). "P4HA1 was mainly expressed in malignant tumor cells and fibroblasts." (PMID 37055822, 2023). "TIMER 2.0 was used to calculate the expression pattern of P4HA1 in different tumor types." (PMID 35812752, 2022). "Taken together, these findings connote that P4HA1 might link angiogenic processes in tumor cells to hypoxic microenvironments." (PMID 35494018, 2022). "The average expression value of P4HA1 was 4.77 in all TCGA tumor tissues." (PMID 34966739, 2021). "P4HA1 overexpression predicted immunosuppressive TIME, which may cause poorer survival in tumor patients with P4HA1 overexpression." (PMID 34966739, 2021). "Numerous studies have demonstrated that high collagen deposition mediated by P4HA1 expression could impact or act as a barrier to tumor immune infiltration." (PMID 34966739, 2021). "Similarly, our results indicated that P4HA1 promoted tumor metastasis through regulating the MMPs and EMT." (PMID 34659558, 2021). "P4HA1 may promote tumor metastasis by enhancing the secretion of collagens, which form together with other extracellular molecules, such as fibronectin and periostin, fibrillar networks that regulate cell motility and invasion." (PMID 32053263, 2020). "However, as an active enzyme in collagen synthesis, we know little about how P4HA1 promotes tumor progression in the past." (PMID 32635458, 2020). "Overexpression of P4HA1 was also observed in tumor tissues (P < 0.001)." (PMID 33299876, 2020). "Its paralog, P4HA1, has been found to promote tumor progression." (PMID 32539762, 2020). "We showed that P4HA1 expression was upregulated in tumor-initiating cell-enriched populations." (PMID 30367042, 2018). "Both P4HA1-shRNA 1 and 2 cells showed significantly reduced tumor growth and weight in mice relative to control animals demonstrating that P4HA1 inhibition attenuates tumor growth and metastasis in vivo." (PMID 25115393, 2014). "However, the role of P4HA1 in the tumor microenvironment still needs to be further explored." (PMID 41469036, 2025). "In patients with HNSC, P4HA1 expression was associated with tumor stage, while P4HA2-3 was not." (PMID 38806556, 2024). "Additionally, we investigated P4HA1 expression at various tumor stages." (PMID 34966739, 2021). "In addition, P4HA1 expression was low in only two tumor types, such as KICH and LAML." (PMID 34966739, 2021). "However, the immunomodulatory role of P4HA1 in tumor immune microenvironment (TIME) remains unclear." (PMID 34966739, 2021). "This identified P4HA1 and HSPA8 as candidate factors underlying gene expression differences in glycolysis-high and -low tumor cells and in other TME stromal cells, respectively, seemed responsible for tumor-specific cell glycolysis phenotypes in hypoxia microenvironment." (PMID 32635458, 2020). "Knockdown of P4HA1 could inhibit tumor growth and neovascularization in vitro and in vivo." (PMID 28415787, 2017). "Furthermore, mouse xenograft studies demonstrated a role for P4HA1 in tumor growth in vivo." (PMID 25115393, 2014). "On closer inspection, however P4HA1 is involved in HIF stabilization and has earned the term surrogate marker for tumor hypoxia." (PMID 40535577, 2025). "The results showed that all genes exhibited significant differential expression in tumor tissues; however, only four genes (CAPS, DAPK1, P4HA1, and PCED1A) demonstrated independent prognostic value." (PMID 40463370, 2025).
tumor (continued). "Prolyl 4-hydroxylase subunit alpha 1 (P4HA1) activates the mevalonate pathway through HMGCS1, suppressing ferroptosis and enhancing tumor proliferation." (PMID 41373599, 2025). "Different genetic settings for P4HA1, MT1-MMP and LOX were tested to assess their impact on the tumour growth." (PMID 39751947, 2025). "This study investigates the role of P4HA1 in CRC, focusing specifically on its impact on tumor growth, metastasis, and TAM infiltration." (PMID 41469036, 2025). "To clarify the role of P4HA1 in CRC progression and tumor immune microenvironment (TIM), we analyzed the P4HA1 expression level in the GEPIA database." (PMID 41469036, 2025). "Our findings elucidate the importance of the P4HA1‐P4HA2‐PI3K‐AKT axis in CRC and identify P4HA1 as a promising therapeutic target to impede CRC growth and metastasis while altering the tumor immune landscape." (PMID 41469036, 2025). "TRAP1 and P4HA1 are highly expressed at the intracellular level, whereas PPARGC1A, EFHD1, and HIGD1A are only expressed by a minority of tumor cells." (PMID 37903487, 2024). "Compared with normal controls, the expression levels of P4HA1, P4HA2, and P4HA3 were significantly higher in tumor tissues, particularly in HNSC." (PMID 38806556, 2024). "The expression levels of SMS, ASNS, PLOD2, P4HA1, PAH, and KYNU were upregulated in tumor samples compared with normal samples, and the remaining three genes were downregulated." (PMID 37511510, 2023). "P4HA1 is a key enzyme in the synthesis of collagen, which is an important component of TME and is involved in the regulation of tumor immunity." (PMID 37055822, 2023). "The interference of the expression levels of SMS, P4HA1, PAH, PLOD2, and KYNU significantly decreased the invasion of tumor cells." (PMID 37511510, 2023). "This study established the differential expression of three key hypoxia genes, ANGPTL4, P4HA1, and VEGFA, which were correlated with several radiomic texture features, mainly focusing on tumour heterogeneity." (PMID 37048688, 2023). "Only P4HA1, PMM2, and AGRN exhibited significant correlation with overall survival (OS), and the transcriptomic expression of P4HA1, PMM2, and AGRN was significantly upregulated in tumor tissues." (PMID 37428395, 2023). "We demonstrated that P4HA1 expression was positively correlated with the expression of TNFSF15, CD80, VTCN1, TNFSF18, and CD200R1 in multiple tumor types but negatively correlated with the expression of CD40LG and CD244." (PMID 35812752, 2022). "Consistent with the RT-qPCR results, Western blot also showed that the protein levels of P4HA1, MLLT11, AURKA, and GOT1 were markedly higher in the tumor tissues than those in the paratumor tissues." (PMID 35558559, 2022). "RT-qPCR results showed that the abundance of P4HA1, MLLT11, AURKA, and GOT1 were significantly elevated in tumor tissues." (PMID 35558559, 2022). "Under a hypoxia microenvironment, the elevated HIF-1α induced the expression of P4HA1, which remodeled ECM and promoted tumor invasion, EMT, angiogenesis, and so on." (PMID 33816483, 2021). "We discovered that the protein levels of HNRNPK, P4HA1, and TUBA4A were significantly upregulated, while CTSL, HNRNPK, and OSBPL5 were significantly downregulated in the tumor tissues compared to those of normal tissues." (PMID 35284334, 2021). "Among these genes, the mRNA levels of ECT2, HNRNPK, P4HA1, and TUBA4A were significantly upregulated in the tumor tissues, when compared to those in normal tissues." (PMID 35284334, 2021). "In addition, HSPA8 and P4HA1 were screened out as the potential modulating factors to glycolysis as their expression were highly correlated with glycolysis score and glycolysis genes, which enables future efforts for therapeutic options to block the glycolysis and control tumor progression." (PMID 32635458, 2020). "HIF-1 facilitates ECM remodeling through upregulating expression of P4HA1, P4HA2, and PLOD2 in hypoxic fibroblasts, which results in tumor invasion and metastasis." (PMID 33299876, 2020).
tumor (continued). "Using global gene expression analysis, we found that a panel of commonly observed hypoxia-inducible genes, including BNIP3L, EGLN3, LOXL4 and P4HA1, were significantly upregulated in the EGFP+ MDA-MB-231 tumor cells, compared to the EGFP− cells." (PMID 29510720, 2018). "To validate the role of P4HA1 in GSC proliferation in vivo, we determined the levels of Ki67 in tumor sections." (PMID 28415787, 2017). "Immunohistochemistry of tumor sections revealed intense HIF-1α staining in perinecrotic (hypoxic) regions, which co-localized with TAZ and with P4HA1, which is a known HIF-1 target gene product." (PMID 25587023, 2014). "Additionally, the knockdown of P4HA1 in CRC cell lines resulted in marked suppression of cell proliferation, migration, and invasion, underscoring its potential role in tumor progression." (PMID 40959429, 2025). "Additionally, HIF-1α recruits TET1 to demethylate the ATF3 promoter, activating ATF3 transcription, which drives alternative splicing of P4HA1 to generate the P4HA1-9a isoform that promotes collagen deposition in the ECM and increases tumor cell invasiveness." (PMID 40813760, 2025). "The total protein levels of P4HA1 in these six tumor types were much higher than those in the negative controls." (PMID 35812752, 2022). "Moreover, six paired fresh tumor tissues and paraneoplastic tissues from children with MRTK were collected to validate the expressions of P4HA1, MLLT11, AURKA, and GOT1 in clinical samples via real-time fluorescence quantitative PCR and Western blot." (PMID 35558559, 2022). "Interestingly, HIF-1α is involved in the regulation of P4HA1 and P4HA2 expression in tumor cells and fibroblasts." (PMID 36140753, 2022). "As the P4HA1‐KD tumors appeared to be highly hemorrhagic, we further studied if there are changes in the amount of type IV collagen (COL‐IV) in the basal lamina of the tumor blood vessels." (PMID 32053263, 2020). "The results demonstrated that overexpression of P4HA1 was prominently correlated with poor prognostic factors involving more advanced stage (stage I vs. II/III/IV, P = 0.009) and greater primary tumor size (T1 vs. T2/T3/T4, P < 0.001) and weakly related to metastasis status (M0 vs. M1, P = 0.066)." (PMID 33299876, 2020). "P4HA1 expression is induced in hypoxia by the hypoxia‐inducible factor 1 (HIF‐1), which regulates several pathways involved in tumor progression, such as EMT, angiogenesis, invasion, inflammation, and tumor metabolism, including the glycolytic pathway." (PMID 32053263, 2020). "Depletion of P4HA1 resulted in significantly reduced tumor weight compared to non-target shRNA-transfected control cells." (PMID 25115393, 2014). "And P4HA1 knocking did not impact tumor weight and main organs of mice." (PMID 41469036, 2025). "We sought to compare the gene expression profiles between tumor cells that were in the top 75% quantile of P4HA1 expression relative to all other tumor cells with non-zero expression of P4HA1, thereby minimizing the impact of drop-out of the single-cell assay on inference of molecular signaling." (PMID 40332386, 2025). "Analysis of the tumor weight 60 days after s.c.injection revealed a higher weight of the tumor masses derived from CAF and lactate scrambled tumor xenografts compared to both DDR1 and P4HA1-silenced counterparts, although not statistically significant." (PMID 38907027, 2024).